EGR1 (early growth response 1)
Diseases named in the same sentence as EGR1 in open-access papers (continued):
Sharing a sentence is not in itself a finding about the gene and the disease.
tumor (continued). "The study also sheds light on the molecular mechanisms involved in MTC metastasis, highlighting the crucial roles of RET, Egr-1 and STAT3 in tumor proliferation, invasion, and angiogenesis." (PMID 37046823, 2023). "Further, gene set variation analysis (GSVA) was used to compare the most upregulated gene, EGR1, and other pathways using a human PDAC dataset 218 primary tumor samples." (PMID 38139993, 2023). "In this study, EGR1 was screened as a potential downstream of CNN2, which possessed a similar expression pattern in CRC (higher in tumor tissues than in normal tissues)." (PMID 37188478, 2023). "Previous findings have shown that tumor cells increase PD-L1 expression through transcription factors such as IRF1/4, c-Myc, EGR1, c-Jun, HIF-1α, NF-κB, ATF3 and STAT3." (PMID 36854755, 2023). "In both cell lines, EGR1 expression was enhanced upon NT157 exposure, which is a tumor suppressor that inhibits cell migration and induces apoptosis in non-small cell lung cancer." (PMID 36224313, 2022). "Although the migration and invasion ability of tumor cells was increased after the EGR-1 knockdown in this study, the experimental data are still insufficient to conclude that EGR-1 is a tumor suppressor in ESSC." (PMID 36233659, 2022). "Among the downregulated genes were several known to activate proliferation of tumor cells (NOTCH1, HMGA2, PTK2, FOSL1, GREM1 and EGR1)." (PMID 35885035, 2022). "EGR-1 enhances the transcription of cell-cycle regulatory proteins such as cyclin D1 that promotes tumor cell proliferation, which in turns activates the MAPK/ERK signaling pathway and auto-activates the expression of EGR-1 through a positive feedback loop." (PMID 35205812, 2022). "Labelled by benign signatures, subclusters 1 and 2 similarly overexpressed metabolism‐related genes and tumour suppressors (KLF6, EGR1, GC, FAM46A, ZFP36, BTG2, etc.)." (PMID 35075805, 2022). "Upon exposure to damaging ionizing radiation EGR1 binds to the 5’ UTR of the PTEN gene, which contains an EBS, a tumor suppressor and pro-apoptotic gene, to induce apoptosis." (PMID 36338037, 2022). "Of note, the early growth response protein 1 (EGR1), which functions as a tumor suppressor in AML, was up-regulated in OCI-AML3 cells in response CIGB-300." (PMID 35359604, 2022). "Its knockdown in different cancer cell lines, including RMS, leads to a deregulation of miR-183–EGR1–PTEN network by upregulating EGR1 and PTEN mRNA levels, as well as EGR1 protein levels, both of which are tumor suppressive." (PMID 36033507, 2022). "LHFPL-AS2, a tumor-suppressive lncRNA in lung cancer, is downregulated under hypoxia due to the reduction in EGR1 expression, resulting in the transcriptional repression of thioredoxin-interacting protein (TXNIP) and promoting tumor metastasis." (PMID 35625948, 2022). "To confirm the tumor repressive effect of EGR1 in NSCLC, we performed IHC staining to evaluate the clinical relevance of EGR1 expression." (PMID 34497759, 2021). "Combined treatment with both GDF15 and EGR1 knockdown resulted in significantly reduced tumor formation, suggesting that the GDF15–EGR1 signaling pathway plays a critical role in HNC progression." (PMID 34681812, 2021). "Recent research suggests that there are overlapping binding sites for Sp-1 and EGR1 in a NGX6 promoter region and that EGR1 increases NGX6 expression and decreases tumor angiogenesis." (PMID 33842351, 2021). "The Egr1 gene was also downregulated in the LPD 35 group and targets the Pten promoter, resulting in tumor cell apoptosis." (PMID 35178394, 2021). "EGR1 can directly increase NGX6 expression by binding to its promoter region and in this way inhibit tumor invasion and metastasis." (PMID 33842351, 2021). "PNA-A15 treatment upregulated A-T repeat-containing genes that act as tumour suppressor genes, such as BAHD1, CCAR1, EGR1, and SLC5A11." (PMID 34059086, 2021). "EGR1 has been shown to down-regulate TERT expression and it has been suggested as a tumor suppressor." (PMID 34282050, 2021).
tumor (continued). "EGR1 can synergistically act with SNAIL on the promoter regions of MMP9 and ZEB1, thereby enhancing their transcription and initiating tumor cell invasion and metastasis." (PMID 33842351, 2021). "In ovarian cancer cells, epidermal growth factor (EGF) has been shown to induce EGR1 and upregulate SLUG, which can decrease the expression of E-cadherin and then enhance tumor metastasis." (PMID 33842351, 2021). "Fluorouracil is widely used in many cancer therapies and is believed to upregulate EGR1 through the p38 MAPK pathway; this drug inhibits tumor angiogenesis." (PMID 33842351, 2021). "When EGR1 is continuously expressed, a variety of antiangiogenic genes are overexpressed, such as CXCL14, TIMP1, TIMP3, and FLT1, which inhibit tumor angiogenesis." (PMID 33842351, 2021). "In xenograft in vivo tumor models, NTPAM inhibited tumor progression of THCA by increasing EGR1 levels." (PMID 33477921, 2021). "The difference in expression comparing tumor and normal tissues were found to be significant in eight genes (PLAU, EGR1, IL6, EGFR, EZH2, BMP4, CCNB1, NMI)." (PMID 34077304, 2021). "The highlight of our study is the remarkable effect on suppressing tumor growth after combined inhibition of both GDF15 and EGR1, compared to inhibition of EGR1 or GDF15 alone in HNC mouse models." (PMID 34681812, 2021). "EGR1, found downregulated in SS specimens and SS18-SSX inducible models, has been suggested as a putative tumor suppressor in this context." (PMID 34857011, 2021). "As shown in the volcano plot, SU decreased GZMB expression and upregulated genes related to inflammatory activation (FOS, JUN, NFKBIA, DUSP2, JAK1, PIM1), tumor immunity (CD47, PCBP2, EIF5A, PDIA3, EGR1), and DNA damage (H2AFX, DDIT3, GADD45B)." (PMID 34824394, 2021). "Among other receptor tyrosine kinases, NTRK1 is a target gene of EGR1 and displays increased mRNA expression in SFT compared to other tumor types." (PMID 34680383, 2021). "In hormone-independent prostate cancer, CXCL5 (also known as ENA78) enhances EGR1 transcription via the RAF–MEK–ERK pathway, thus increasing SNAIL expression, tumor cell metastasis, and EMT." (PMID 33842351, 2021). "Overexpressed EGR1 binds to the thrombospondin 1 (TSP1) promoter, enhances TSP1 expression, and diminishes tumor angiogenesis." (PMID 33842351, 2021). "Serum addition or mitogen treatment with the tumor promoter TPA (tetradecanoyl phorbol acetate) on mouse fibroblasts led to a rapid and strong induction of an early growth response gene then named Egr1." (PMID 32121305, 2020). "As revealed from the results, lower EGR1, EGR2, and EGR3 levels displayed a relationship to higher SBR grade, NPI, and tumor stage, respectively (p < 0.0001)." (PMID 33614706, 2020). "CT-PCs converted to TICs could acquire SS-induced genes, such as Egr1, Ap1, Epcam, Jun, and several Klf family genes, upon +SS application, suggesting that stress-responsive signaling pathways are hypersensitive in CT + SS cells compared with their parental tumor cells." (PMID 30651129, 2019). "NGFI-A binding protein 2 (NAB2) represses the transcriptional activation of early growth response protein-1 (EGR1), a tumor-suppressor." (PMID 30845713, 2019). "Our data suggest that upregulation of NAB2, a corepressor of EGR1, permits EGF-mediated cancer invasion during conditions of EGR1 overexpression through the transactivation of Sp1-dependent tumor-promoting genes." (PMID 30845713, 2019). "Previous studies showed that both D281G and R248W mutants transactivate expression of tumor progression-related genes such as MYC, PCNA, EGFR, and EGR1; the D281G mutant shows an even greater transactivating activity than R248W in these studies." (PMID 30862120, 2019). "Other candidates such as EGR1, RUNX2, STAT1, TRAP2, IRF1 and USF1 have been experimentally validated as drug targets, metastasis promoter or tumor growth enhancers, see19–24." (PMID 31857653, 2019).
tumor (continued). "Tumor specimens from 53 patients with NSCLC and Xenograft models was also utilized to explore the regulatory relationship of CTSL, TGF-β, Egr-1 and CREB." (PMID 31370861, 2019). "c-JUN, which is also an ERK responsive gene, was regulated in the opposite direction as EGR1. rHE4 treatment upregulated expression of c-JUN, which is consistent with its role as a promoter of tumor growth and proliferation." (PMID 31164954, 2019). "To this end, we injected A549-Oct4 cells subcutaneously into NOD/SCID mice and examined the expression of Oct4, Egr1 and OPN in tumor tissues by immunohistochemical staining after 60 days." (PMID 31399076, 2019). "Taken together, the additive and sequential interactions of HIF1α, EGR1 and SP1 finely mediate EPO-R expression in NSCLC under hypoxia, which affects NSCLC progression and makes it response sensitively to the tumor microenvironment." (PMID 31752873, 2019). "DNAzyme (a 33-nucleotide ssDNA) was particularly designed with sequence in complementary to part of target EGR-1 mRNA, which generally exists in the cytoplasm of normal cells but over-expressed in MCF-7 human breast cancer cells." (PMID 29615605, 2018). "Egr-1, as an immediate-early response protein, has been considered to play a crucial role in the process of EMT in a variety of tumor cells." (PMID 30050950, 2018). "To understand the function of EGR1 in RMS, we first assayed for the expression of EGR1 in RMS tumor cell lines representing both ERMS and ARMS and a normal myoblast cell line, C2C12, an immortal murine cell line used as a model for normal myogenesis." (PMID 29719592, 2018). "The boxplots showed that the expression level of EGR1, FOS, and FOSB was significantly lower in primary tumor than that in the normal liver for LIHC patients from TCGA (p<0.001)." (PMID 30228980, 2018). "We further found that egr1, a flow responsive transcription factor gene involved in FGF-dependent angiogenesis during neo-vascularization and tumor growth, is downregulated in klf2 mutant hearts." (PMID 30592462, 2018). "We then expanded this analysis to additional targets including cystatin 6 (CST6), a cysteine protease inhibitor which functions as a tumor suppressor and has been identified as a repression target of TBX2 through a mechanism involving EGR1." (PMID 29719592, 2018). "The knockdown of this miRNA leads to increased mRNA and protein levels of EGR1 and PTEN, two tumour suppressors." (PMID 28895916, 2017). "Here, the authors show that microRNA192 has anti-angiogenic functions and negatively regulates EGR1 and HOXB9, and that delivery of this microRNA to tumours in vivo can reduce angiogenesis and tumour growth." (PMID 27041221, 2016). "The expression of both EGR1 and HOXB9 in tumours completely abrogated the anti-tumour effect of miR-192." (PMID 27041221, 2016). "EGR1 (ZNF225, KROX24, AT225) is a highly regulated putative tumor suppressor gene that regulates the transcription of genes involved in multiple cellular processes such as inflammation and apoptosis." (PMID 25710169, 2015). "A calculation of the Pearson correlation coefficient between EGR1 and TTP expression in normal and tumor tissues gave a value of r = 0.84 indicating a high positive correlation." (PMID 26343742, 2015). "Co-expression of PRR11, UCHL1, EGR1, and SNAT1 was found to be a frequent event in HC tumor samples, indicating a cross-talk among these four proteins." (PMID 25971332, 2015).
tumor (continued). "In addition, as the NAB2-STAT6 fusion leads to EGR1 (early growth response protein 1) activation and transcriptional deregulation of EGR1-dependent target genes, we immunohistochemically evaluated the expression of EGR1 in our tumor samples in order to semi-quantify EGR1 protein levels in SFT." (PMID 25432794, 2014). "Egr-1, first discovered as a gene rapidly induced in response to serum, has been shown to regulate FGF2 levels during angiogenesis and tumour growth." (PMID 24651658, 2014). "Other genes similarly regulated include DUSP1, EGR1, EGR2, JUN, and NR4A1, which are components of the TTP-low tumor gene signature, again linking TTP levels and innate immunity." (PMID 25541715, 2014). "For example, TXNIP (thioredoxin-interacting protein), EGR1, CBX7, HOXA9 and FOXN3 (checkpoint repressor 1) have tumor suppressor functions and are targeted by the potentially oncogenic miRNA miR-93, miR-183, miR-181b, miR-182 and miR-7." (PMID 21375733, 2011). "On the other hand, stable expression of EGR1 inhibited cell proliferation and soft agar growth in NIH3T3 cells transformed with v-sis, indicating that EGR1 functions as a tumor suppressor." (PMID 21283769, 2011). "Instead, Snail's tumor-promoting activity is largely mediated through its cooperation with EGR1/SP1 transcription factors on non-canonical TCACA promoter elements, which upregulate genes such as ZEB1, MMP9, and LEF1." (PMID 42152116, 2026). "Together with our results, it seems that EGR1 and CXCR4 might be actively secreted into small EVs by CRC tumor cells to subsequently participate in intercellular communication and provide an optimal microenvironment for the establishment of distant metastases." (PMID 40635521, 2025). "Sherry Y's team confirmed that miR‐192, EGR1 and HOXB9 might be regulated by the same upstream factors and thus participate in tumour angiogenesis and invasion." (PMID 40936205, 2025). "Besides, the TCGA database confirmed that the level of EGR1 in LUSC and LUAD tumor tissues was significantly decreased compared with normal tissues." (PMID 38244586, 2024). "We could show that the original tumor and both primary RB cell lines (RB and MEGM) clustered together with only one DEG identified in each group (EGR1 in the MEGM and NPVF in the RB group)." (PMID 39695086, 2024). "The KLF6, MYC, and FOSL2 genes did not seem to follow the EGR1/FOS expression pattern in the analyzed tumor samples." (PMID 39436655, 2024). "EGR1's influence extends further when it promotes cell-cycle regulatory factors such as cyclin D1 and activates the MAPK/ERK pathway, creating a positive feedback loop significantly fueling tumor growth." (PMID 39120790, 2024). "Notably, among the most variable genes, we identified EGR1, the downstream effector of the MAPK signaling pathway, which performs the regulatory function in cell proliferation, tumor invasion, and immune regulation." (PMID 37958905, 2023). "Importantly, ChIP assay results revealed that the binding between the EGR1 protein and Gαi2 DNA promoter sequence was significantly increased in HCC tumor tissues of four different primary HCC patients (Patient-1#/-2#/-3#/-4#)." (PMID 36805440, 2023). "Besides, we found patients with higher expression of EGR1 were correlated with higher tumor N stage (p < 0.05) and TNM stage (p < 0.05), indicating the tumor-promoting role of EGR1." (PMID 36932397, 2023).
tumor (continued). "We further constructed gene modules in AT2 (LUAD) and basal (LUSC) cells, which revealed that many tumor-related genes in cells from stage-I patients, including PIGR, AZGP1, BTG2, EGR1, and LMO3 in AT2 cells from LUAD, and AQP3, SPHK1, PPT1, and PDIA6 were found in basal cells from LUSC." (PMID 35027529, 2022). "Moreover, inhibition of EGR-1 expression decreases the proliferation and migration of microvascular endothelial cells and reduces VEGF expression and tumor angiogenesis." (PMID 36276117, 2022). "EGR1 may regulate PTEN expression by targeting the PTEN promoter, thus resulting in tumor cell apoptosis." (PMID 33842351, 2021). "We confirmed that the protein expression of p-ERK and p-AKT in tumor tissues synergistically decreased along with GDF15 and EGR1 in the combined treatment group compared to the single treatment groups, whereas the total level of AKT and ERK protein were not affected." (PMID 34681812, 2021). "EGR1 and GADD45α were increased in NTPAM-treated mouse tumor tissues compared with control tissues." (PMID 33477921, 2021). "EGR1 also increases tumor cell apoptosis by directly upregulating tumor suppressors called non-steroidal anti-inflammatory drug (NSAID)-activated gene 1 (NAG1) and PTEN." (PMID 33842351, 2021). "Subsequently, through literature reviews about EGR1, JUN, and EZH2, we recognized that EGR1 and JUN could be tumor suppressors, whereas EZH2 can inhibit the expression of tumor suppressors." (PMID 34966410, 2021). "As a result, several hub DEFs with maximum intramodular connectivity were identified (e.g., SOX4, EGR1, LEF1, FOS, MITF, KLF4, TCF7, and KDM6B), which might involve CD248-mediated tumor-promoting regulation in CAFs." (PMID 34970489, 2021). "Under hypoxic conditions, EGR1 increases VEGFA expression, mediated by HIF1α, and directly activates VEGFA transcription, thus promoting the formation of blood and lymphatic vessels in the tumor." (PMID 33842351, 2021). "In those studies, normal and/or tumor tissues that underwent warm ischemia due to delayed processing after surgical incision demonstrated increased expression of FOS, FOSB, JUN, EGR1 as well as upregulation in immune system pathways compared to tissues processes immediately." (PMID 34814833, 2021). "Our findings show that the GDF15–EGR1 signaling axis may play a pivotal role in the regulation of tumor progression, since GDF15 activated tumor progression via EGR1 activation and EGR1 positively regulated GDF15 expression in HNC cells." (PMID 34681812, 2021). "Although for genes like Il15 we did not observe any difference between healthy and tumor-bearing mice in Ficoll or Parsortix samples; others, such as Egr1, Zc3h12a, Klf4, or Nfat5, allowed distinguishing for cancer or CTC presence." (PMID 35153760, 2021). "3.3, we show the nodes having high role A and B motif centrality, such as HIFs, HDAC, BRCA1, EGR1, STAT1, GATA1 and GATA3, and also report their functions as master regulators in liver function, cell proliferation, tumor suppression and genomic stability, etc. as well as stress response." (PMID 32541819, 2020). "Ivy GAP mRNA data showed a trending decline in EGR1 mRNA levels from central tumour to intermediate and periphery, however, the results were non-significant (P = 0.07)." (PMID 32518380, 2020). "The same results were found when analysing TCGA EGR1 mRNA data, which furthermore showed that the expression of EGR1 mRNA in normal brain tissue was significantly lower than in tumour tissue (data not shown)." (PMID 32518380, 2020). "Expression of SS-induced genes, such as Early growth response 1 (Egr1), Activator protein 1 (Ap1), Epithelial cell adhesion molecule (Epcam), and Kruppel-like factor 8 (Klf8), were the highest in the circulating GFP+ tumor cells." (PMID 30651129, 2019).